CXCL10 (C-X-C motif chemokine ligand 10)
Diseases named in the same sentence as CXCL10 in open-access papers (continued):
Sharing a sentence is not in itself a finding about the gene and the disease.
tumor (continued). "Expression of CXCL5, CXCL9, and CXCL10 was significantly negatively correlated with tumor purity." (PMID 33323542, 2020). "Thus, our new data suggests that previously reported inhibition of tumor angiogenesis is a secondary effect caused by earlier infiltration with M1-polarized macrophages producing increased CXCL9 and CXCL10." (PMID 31831780, 2019). "However, the data presented here suggest that a major role for CXCL10 would be in mediating the recruitment of effector cells towards the tumor site, and that BCG can facilitate the upregulation of the CXCR3 receptor in this context." (PMID 31277459, 2019). "After the administration of IVT-B2 RNA, active NK cells might be attracted to the tumor via chemoattractant CXCL10, and the IFN-β might enhance NK cell activity in the tumor microenvironment." (PMID 31447826, 2019). "CXCL10 is secreted by several cell types (including monocytes, endothelial cells, and fibroblasts), and attracts granulocytes and effector leukocytes to the bladder for tumor elimination." (PMID 31277459, 2019). "Our findings further demonstrated that deletion of Camkk2 in BMDM also results in increased expression of genes encoding CXCL9 and CXCL10 chemokines that attract and activate CXCR3 expressing cells, including Th1, CD8+ T cells, and NK cells, which positively regulate anti-tumor immunity." (PMID 31164648, 2019). "Collectively, these results indicate that GBE1 blockade induces IFN-I production via STING signaling pathway, accompanied by upregulation of PD-L1 in LUAD cells, which further enhances the secretion of CCL5 and CXCL10 to recruit CD8+ T lymphocytes in the tumor microenvironment." (PMID 31221150, 2019). "When investigating the plasma concentration of the CXCR3 ligands CXCL9 and CXCL10 in tumor patients treated with anti-PD-1 alone or anti-PD-1 and anti-CTLA-4 antibodies, it was found that the treatment responder group has elevated levels within the first few months after therapy." (PMID 31557787, 2019). "Furthermore, when tumour-bearing DCs were co-cultured with cryo-thermal eosinophils, the expression level of pro-inflammatory cytokines (CXCL10, IL-1β, IL-15 and IL-6) was increased as compared to tumour-bearing DCs co-cultured with tumour-bearing eosinophils." (PMID 31519961, 2019). "Eosinophils may promote antitumor immunity by recruiting CD8+ T cells to the tumor microenvironment via secretion of chemoattractants (CCL5, CXCL9, and CXCL10) and normalization of tumor vasculature, thereby allowing for increased effector T cell infiltration." (PMID 31730503, 2019). "By maintaining high CXCL9/CXCL10 levels within the tumour, these ligands could interact with their cognate receptor, CXCR3, which was observed to be expressed higher on pre-cDC1 in the blood than on other DCs subsets." (PMID 31091774, 2019). "Moreover, neutralization of CXCL10 with anti-CXCL10 antibody inhibited the effect of M2 macrophages promoting tumor migration." (PMID 31296243, 2019). "As CXCR3-mediated recruitment appears crucial for T cell entry into tumors and as Treg reduce CXCL9 and CXCL10 expression in tumors, we were eager to determine the source of CXCL10 in tumor tissue, and determine if CXCL10-producing cells were indeed affected by Treg depletion." (PMID 29671006, 2018). "The data from this study could suggest that CXCL9 and CXCL10 could play a role in tumor angiogenesis, as down regulation of which on the CVMSCs, have affected MDA-MB231/HUVECs tube formation." (PMID 30458011, 2018). "Consistently, CXCL10 was strongly induced by interferon gamma in normal and tumor thyrocytes." (PMID 29416784, 2018). "In addition to IFN-β or TRAIL, there are several other tumor-suppressor genes and cytokines with anticancer activities, such as CXCL10, IL-12, and pigment epithelium-derived factor (PEDF), which are utilized for the genetic modification of ADSCs." (PMID 30445793, 2018).
tumor (continued). "In addition, in the histological verification experiment, differential expressions of the two main target genes GDF5 and CXCL10 were observed between EBVaGC and non-tumor tissues as well as EBVnGC." (PMID 30258285, 2018). "CXCL10 is a strong angiostatic factors, and it may be involved in the recruitment of tumour-infiltrating T cells." (PMID 30258285, 2018). "Moreover, radiation-induced tumor lysis led to a decrease in tumor CXCL10 secretion, while the levels of CXCL16 secreted by the APCs into the circulation increased, thereby attracting T cells to the TME and increasing the number of TILs." (PMID 30519541, 2018). "In addition, CXCL10 also prevents tumor angiogenesis by blocking endothelial cell proliferation and consequently a decrease in microvessel density as observed in melanoma tumor xenografts." (PMID 29780381, 2018). "Indeed, chemokines such as CCL3, CCL4, CCL5 and CXCL10 were significantly increased in tumours injected with MV-Edm." (PMID 28701757, 2017). "CXCL10 was constantly high in both tumours and GRO was mildly expressed in all passages." (PMID 28386296, 2017). "Elevated serum CXCL10 and increased expression of CXCL10 and CXCR3 in tumor cells have been associated with a poor prognosis and metastasis (50, 51, 56, –, 58), suggesting that the CXCL10–CXCR3 axis may promote CRC progression in some cases." (PMID 28717003, 2017). "IFN-γ and CXCL10 increased time dependently in the tumor tissue." (PMID 28931823, 2017). "Additionally, their induction of type I IFN secretion by dying tumor cells can also lead to autocrine signals that trigger release of chemokines such as CXCL10 that promote recruitment of immune cell populations to the tumor." (PMID 29209327, 2017). "Finally, we show that RRS strikingly elevated CXCL10 in tumor tissue, an effect reversed by propranolol." (PMID 28603578, 2017). "Although the chemokine CXCL10 is known to exert anti-angiogenic properties and mediate the recruitment of CXCR3-expressing mononuclear cells with anti-tumor activities, CXCL10 and its receptor CXCR3 are increasingly being recognized as pro-tumorigenic in several types of cancers, including CRC." (PMID 28717003, 2017). "One might expect that production of CXCL10 by epithelial cells will recruit T cell and NK cells to areas of epithelial cell transformation and accelerate tumor clearance." (PMID 28567040, 2017). "The increased macrophage recruitment may be a response to the increased chemokine release by tumor cells such as CXCL-10, CCL-2, CCL3, CCL4, and CCL5." (PMID 28670313, 2017). "In addition, systematically administered bacterial OMVs target and accumulate in the tumor tissue, and subsequently induce the production of antitumor cytokines CXCL10 and interferon (IFN)-γ." (PMID 28931823, 2017). "Moreover, systematically administered bacterial outer membrane vesicles specifically target and accumulate in the tumor tissue, and subsequently induce the production of antitumor cytokines CXCL10 and interferon-γ." (PMID 28931823, 2017). "Adding galectin antagonists also boosted IFNγ-induced CXCL10 production in tumor xenografts." (PMID 28986561, 2017). "Similarly, triggering MDA5 activation by using synthetic double-stranded RNA-poly(I:C) in ovarian cancer exhibits enhanced expression of HLA-class I, release of cytokines (CXCL10, IL-6, and type I interferon), as well as tumor cell apoptosis." (PMID 28216575, 2017). "Additionally, the expression levels of mRNA for IFN-γ, CXCL9 and CXCL10 were significantly elevated in the tumor tissues." (PMID 28881713, 2017). "However, their increased efficacy in vivo was also found to be dependent upon secondary overexpression of CXCR3, the main receptor for the IFNγ-dependent chemokine ligands CXCL-9 and CXCL-10 found at elevated levels the TME of inflamed tumours." (PMID 29157300, 2017).
tumor (continued). "Finally, analysis of tumor protein lysates on antibody microarrays demonstrated an increase in pro-inflammatory cytokines, such as CXCL10, and a decrease in angiogenic proteins in debulking + anti-CD47 vs non-debulking + IgG tumors." (PMID 28076333, 2017). "The importance of adaptive immunity is underscored by our finding that cancer-cell derived CXCL10 did not protect from tumor formation in T- and B-cell deficient mice." (PMID 29163806, 2017). "In addition, activated macrophages are the cells that secrete most chemokines, including CXCL9 and CXCL10, into the tumor environment." (PMID 28076333, 2017). "Cytokine analysis of serum obtained from treated mice demonstrated a surge in IFN-γ, IL-6, and CXCL10 concentrations prior to peak T cell expansion, which also returned to background levels post tumor elimination and following contraction of T cell density in the lungs to background levels." (PMID 29085043, 2017). "IP-10 (CXCL-10), the top protein biomarker is a pro-inflammatory chemokine, which has been highly associated as a biomarker to predict severity of several inflammatory diseases including infectious diseases, immune dysfunction and tumor development." (PMID 27286230, 2016). "Moreover, we confirmed that CXCL10 and CXCL11 are the key chemokines in neuroendocrine-like cells and they promote the chemotaxis activity of tumor-associated macrophages." (PMID 27034164, 2016). "LTβR signalling is well known to recruit lymphoid and myeloid cells into lymphoid organs and tumours, and activation mediates accumulation of macrophages and NKT/T cells in association with increased expression of CXCL10 and CCL2 in AKT/CAT and AKT/NICD tumours." (PMID 26206664, 2016). "In addition, downregulation of SK1 in B16 led to an increased expression of Th1 cytokines (IL-12, TNFa, IFNg) and chemokines (CCL5, CXCL9, CXCL10) into the tumor." (PMID 27708249, 2016). "FIP200-deficient tumor cells showed an upregulated expression of genes implicated in IFN signaling and an increased production of the chemokine CXCL10 that may favor infiltration of CD8+ T lymphocytes." (PMID 27917371, 2016). "Our data demonstrated increased levels of CXCL10 in serum and tumor tissues of MSCs-Sirt1 mice." (PMID 27764779, 2016). "In addition to its cytolytic effects, IFN-γ can also induce tumor cells to produce chemokines that attract immune effector cells, such as CXCL10 (IP-10)." (PMID 26741508, 2016). "Expression of CXCL10 mRNA was also increased in tumor tissues of MSCs-Sirt1 group." (PMID 27764779, 2016). "This is consistent with the detection of CXCL9 and CXCL10 mRNA in spleens, lymph nodes and tumours." (PMID 25495686, 2015). "In addition, the combined treatment of CXCL10 gene therapy and radiotherapy inhibited tumor growth more effectively compared with all other groups (P<0.05)." (PMID 26622567, 2015). "Tumor-derived CXCL10 and CXCL12 may have played a role in the massive infiltration of leukocytes to low generation xenografts." (PMID 26291724, 2015). "To determine whether CXCR3 was required for intra-tumoural recruitment of CD4+ T cells we tested whether CXCR3-desensitization through pre-incubation with CXCL10 would interfere with the ability of adoptively transferred T cells to access the tumour." (PMID 25495686, 2015). "Furthermore, tumor-derived chemokines that promote leukocyte migration and their entry into the CNS such as CXCL-10 and CXCL-12 are down-regulated, and the levels of TGF-β2 increase." (PMID 26291724, 2015). "Importantly, prevailing among all the different molecules that were identified in the co-culture of the three cell types was CCL2, followed by IP-10 (CXCL10) and IL-6, confirming the central role of these molecules in this tumor model." (PMID 25599228, 2015).
tumor (continued). "In tumor lesions, the local expression of CCL5 and CXCL10 was positively associated with the expression of the CD8+ T lymphocyte markers CD8 and Granzyme B (RCD8 = 0.2338, pCD8 < 0.01, RGranB = 0.5517, pGranB < 0.001; RCD8 = 0.2972, pCD8 < 0.005, RGranB = 0.3204, pGranB < 0.001)." (PMID 26317795, 2015). "CXCL10 levels were 271.4 ± 10 pg/mg in tumor tissue and 74.1 ± 10.9 pg/mg in spleens." (PMID 25798946, 2015). "Of these genes, IL-4 and CXCL10 were newly identified DEGs that may contributed to tumor suppression." (PMID 25108500, 2014). "Furthermore, we observed that the protein levels of CXCL10 in tumour and normal tissue were significantly positively correlated (r=0,60, P<0.001) (data not shown)." (PMID 24748971, 2014). "Among the upregulated genes, we identified several oncogenes (Ets2, Fyn, Fos, Rab30 and Src), various tumor markers (Cyp1b1, Gpa33, Cd47, Fam129a, st7l, chka, Lgalsbp, Antxr1 and Ly6a) and other genes related to tumor promotion (Cxcl10, Trim25, Grn, Foxc2, Bmp7 and Irs1)." (PMID 23936067, 2013). "Multiple mechanisms were proposed to contribute to this synergy, including CXCL10-mediated recruitment of activated T and NK lymphocytes to the tumor, inhibition of tumor angiogenesis by CXCL10, and TNF-alpha-mediated tumor necrosis and maturation of dendritic cells." (PMID 24202446, 2013). "Th17 cells may contribute to protective human tumor immunity by inducing Th1-type chemokines and stimulating CXCL9 and CXCL10 production to recruit effector cells to the tumor microenvironment." (PMID 22693525, 2012). "Tumor samples were also stained with anti-MIG/CXCL9 or anti-IP10/CXCL10 antibodies." (PMID 21067607, 2010). "Notably, three genes in the classifier for the tumor stroma, CXCL10, CXCL11, and ISG20, are known interferon γ-regulated genes." (PMID 19225562, 2009). "In murine studies, CCL21-DC induced tumor regression, stimulated production of IFN-γ and the CXC chemokines MIG (CXCL9) and IP-10 (CXCL10) at the tumor site, and decreased local concentrations of immunosuppressive inflammatory mediators including IL-10, PGE2, and TGF-β." (PMID 18644162, 2008). "Both CXCL9/MIG and CXCL10/IP-10 are chemotactic for stimulated CXCR3-expressing T lymphocytes that could further amplify IFN-γ at the tumour site." (PMID 16598185, 2006). "The induction of CXCL9/CXCL9/MIG and CXCL10/CXCL10/IP-10 may be responsible in part for the tumour reduction following CCL19 administration." (PMID 16598185, 2006). "However, even in HGSOC itself, this distinguishes CX3CL1 from other T-cell recruiting chemokines such as CXCL9 and CXCL10, which can combat tumour growth in vivo by enhancing lymphocyte infiltration and represent a strong and robust protective prognostic marker." (PMID 39862711, 2025). "Moreover, it has been reported that the T cells activated by radiotherapy are recruited to new tumor sites by the CXCL10 secreted by tumor cells, and the release of HMGB1 facilitates the synthesis of pro‐inflammatory factors, including type I interferons, subsequently guiding CXCL10 production." (PMID 40387011, 2025). "Furthermore, since CXCL10 can modulate the physical tumor barrier, treatment with TNFα can increase vascular permeability, facilitating the extravasation of NP-encapsulated chemotherapy into the tumor, underscoring the versatility of this approach in combination with chemokine-based therapies." (PMID 41516196, 2025). "In addition, the tumor-immune correlation analysis demonstrated that PHF8 expression was strongly negatively associated with the levels of MHC class I genes including B2M, HLA-A/B/C, TAP1/2 as well as chemokines such as CCL5 and CXCL10." (PMID 40001243, 2025). "While the magnitude of increase in IFNγ and CXCL10 in response to αCD3/αCD28 between cross-well and sequential treatment varied, the directionality of response was in high agreement with 5/6 tumor samples showing >1.5 fold change for IFNγ and all tumor samples showing >1.5 fold change for CXCL10." (PMID 40791544, 2025).
tumor (continued). "Notably, certain studies indicate that, under specific tumor types and microenvironmental conditions, CXCL10 may play a role in inhibiting tumor progression by facilitating immune cell chemotaxis, suppressing angiogenesis, and promoting apoptosis in tumor." (PMID 40129528, 2025). "Additionally, the upregulation of chemokine genes such as CXCL9 and CXCL10 may facilitate T cell migration to the tumor microenvironment, further strengthening their immune surveillance capabilities." (PMID 40534857, 2025). "Importantly, the observed TME remodeling was not merely a bystander effect but a direct consequence of CAR-M’s ability to simultaneously eliminate tumor cells and secrete chemotactic signals like Cxcl10, which recruits CXCR3+ T cells to establish an inflamed microenvironment." (PMID 41388305, 2025). "These cells express Cxcl9, Cxcl10 and Il15, but in contrast to type 1 conventional dendritic cells, which cross-present antigens, inflammatory monocytes obtain and present peptide–major histocompatibility complex class I complexes from tumour cells through ‘cross-dressing’." (PMID 39604727, 2025). "Furthermore, future clinical studies should evaluate whether the ratio of CXCR3-A to CXCR3-B expression on circulating immune cells and tumor cells, combined with serum CXCL10 levels, serves as a more precise prognostic indicator of metastatic susceptibility." (PMID 41516196, 2025). "We next evaluated whether the tumor growth inhibition observed in Ackr2-targeted B16-F10 cells is associated with changes in immune cell infiltration, likely driven by altered availability of key chemokines such as CCL5 and CXCL10." (PMID 40248897, 2025). "Thus, we speculated that inhibiting HMGB2 contributed to an inflammatory tumor environment by promoting CXCL10 secretion." (PMID 40315321, 2025). "In developing therapeutic ‎interventions, combining CXCL10 gene ‎therapy ‎with conventional cancer treatments such as ‎chemotherapy and radiotherapy could be ‎explored as ‎a synergistic approach to improve anti-‎tumor efficacy." (PMID 40760734, 2025). "The complex biology of the CXCL10 axis, with its opposing functions, makes it a good candidate for combination therapies and sophisticated delivery systems that can exert spatial and temporal control over chemokine signaling, immune recruitment, and tumor targeting." (PMID 41516196, 2025). "Moreover, DPP-4i could have anti-cancer effects by modulating the DPP-4/SDF-1/CXCR4 axis and the immune balance, enhancing tumor rejection by preserving biologically active CXCL10 and increasing trafficking into the tumor by lymphocytes." (PMID 40175622, 2025). "Moreover, tumour-derived nitric oxide similarly downregulates CXCL10, impairing T-cell migration." (PMID 40361472, 2025). "Therefore, CXCL10 can either enhance anti-tumor immunity by recruiting cytotoxic T cells and activating inflammatory responses, or conversely contribute to immunosuppression and resistance to therapy, depending on the tumor context and the involvement of downstream signaling pathways." (PMID 40760734, 2025). "As a possible approach is to use viral vectors such as lentiviruses or adenoviruses, as well as non-viral carriers such as nanoparticles and liposomes, may be employed to deliver the CXCL10 gene directly into tumor or immune cells to enhance local expression and boost the anti-tumor immune response." (PMID 40760734, 2025). "Specifically, the use of photoconvertible immune cell reporters (e.g., Kaede or KikGR mice) and longitudinal in vivo imaging could be employed to definitively demonstrate the sequestration of CXCR3+ effector cells in the lungs or circulation in response to tumor-driven CXCL10 gradients." (PMID 41516196, 2025). "However, the role of CXCL10 in angiogenesis could be tumor-specific, meaning that inhibition of CXCL10 could have different effects depending on the type of cancer, necessitating a tailored approach for different tumor situations." (PMID 40760734, 2025).